AKT2 (AKT serine/threonine kinase 2)
Diseases named in the same sentence as AKT2 in open-access papers (continued):
Sharing a sentence is not in itself a finding about the gene and the disease.
diabetes (52 papers, 2008 to 2025). "We describe herein the effects of a spontaneous Akt2 deficiency in a colony of NOD mice exhibiting a phenotype of early diabetes." (PMID 38643275, 2024). "Loss of Akt2 also inhibited diabetes-induced elevation of RNA and protein levels of the EMT markers Snail/Slug and Twist1 in the RPE as compared to Akt2fl/fl diabetic mice." (PMID 37443129, 2023). "This is also true in humans with a germline mutation in Akt2 that causes diabetes, in which the mutation which inhibits Akt2 activity, and the resulting mutant perhaps acts as dominant negative over the other Akt isoforms." (PMID 35578699, 2021). "A loss-of-function mutation in the AKT2 gene is the cause of a subtype of the rare disease familial partial lipodystrophy that results in severe insulin resistance and leads to early onset diabetes mellitus with lipodystrophy and hyperinsulinemia." (PMID 31835296, 2019). "Patients that carry a partial loss-of-function variant of AKT2 tend to have a higher level of fasting plasma insulin and an increased risk of developing diabetes mellitus." (PMID 31835296, 2019). "As for Akt1, the Akt2 isoform regulates beta-cell growth and survival; however, Akt2 distinctively controls glucose metabolism as Akt2-deficient mice develop diabetes." (PMID 22563476, 2012). "From these perspectives, an additional explanation is required for progression of diabetes and tissue damage in hypoinsulinemic status, like type I diabetes, Akt2 deficiency or nNOS knocked out mice." (PMID 18335029, 2008). "Since loss of Akt2 function in the RPE protected against diabetes-induced retinopathy, we examined whether increased Akt2 would have the reverse effect by generating RPE-specific Akt2 KI mice and inducing diabetes with STZ." (PMID 36229454, 2022). "Akt2 deficiency in mice was documented to induce hyperinsulinemia, which precludes inhibition of tumorigenesis, and if partial deficiency of Akt1 also occurred, the mice developed hyperglycemia and diabetes." (PMID 35578699, 2021). "Patients with inactivating mutations of AKT2 develop hyperinsulinemia, hypodystrophy, and early onset diabetes, and we used metabolic profiling of AKT2 KO hPSC-ECs to show the expected decrease in glucose catabolism (higher levels of G6P and a tendency toward higher ATP levels)." (PMID 31835296, 2019). "The AKT2 isoform, for example, has been implicated in diabetes." (PMID 29173281, 2017). "Akt2 deficiency in mice causes a mildly diabetes mellitus phenotype." (PMID 25888638, 2015). "Overall results suggest that AKT1 can compensate for an AKT2 deficiency with regard to glucose homeostasis and diabetes, and that AKT isoforms may have complementary and compensatory roles in glucose homeostasis in vivo." (PMID 22680924, 2012). "Additionally, some rare loss-of-function alterations of AKT2 have been reported in monogenic forms of diabetes, and may also play a role in MODY development." (PMID 39201476, 2024). "Knockout of Akt2 could cause IR and diabetes in the liver and skeletal muscle." (PMID 38018594, 2023). "Importantly, we found that blocking Akt2 signaling using Akt2 siRNA significantly inhibited high glucose-induced human fRPE cell migration compared to the control group (siCtrl), suggesting that Akt2 signaling contributes to the RPE cell migration/EMT process caused by diabetes." (PMID 37443129, 2023). "In addition to NKX6–1 we found variants in WFS1, RFX6 and 7 other genes associated with monogenic forms of diabetes (AKT2, EIF2AK3, GLIS3, HADH, MNX1, NKX2–2, and PTF1A) and they may be relevant to development of MODY." (PMID 29439679, 2018). "Importantly, Akt2-deficient mice develop mild to severe diabetes with high beta-cell loss." (PMID 22563476, 2012). "Western blotting indicated that both Akt2 expression and phospho-GSK3β (ser9), the inactive form of GSK3β, were decreased during diabetes." (PMID 38581667, 2024). "Data shows that PI3K/Akt2/ERK signaling contributes to the diabetes-induced retinal fibrosis process." (PMID 37443129, 2023).
diabetes (continued). "To investigate the role of Akt in the retinal fibrogenesis in diabetes, we first examined the levels of phospho- and total Akt1 and Akt2 protein in RPE from diabetic mouse and human DR cadaver tissue." (PMID 37443129, 2023). "Here, we show that the RPE-specific knockout of Akt2 attenuates diabetes-induced increases of EMT and fibrosis markers." (PMID 37443129, 2023). "We also found that in Akt2 cKO mice diabetes-induced increase of fibrosis markers, including collagen IV, Connective tissue growth factor (CTGF), fibronectin, and alpha-SMA was attenuated." (PMID 37443129, 2023). "To investigate if Akt2 contributes to the diabetes-induced retinal fibrosis process, we immunostained for the fibrosis marker alpha-SMA in RPE cells." (PMID 37443129, 2023). "To investigate if EMT markers are associated with elevated Akt2 in the RPE of diabetic mice, we evaluated mRNA levels in the RPE of mice after an 8-month duration (10 months of age) of diabetes." (PMID 37443129, 2023). "RPE-specific knockout of Akt2 attenuates diabetes-induced retinal molecular alterations and vascular lesions." (PMID 36229454, 2022). "Taken together, these data suggest that Akt2 in the RPE promotes the diabetes-induced increase of neural retinal inflammation that mediates leukostasis within the retinal vasculature through ICAM-1." (PMID 36229454, 2022). "Knocking out Akt2 specifically in the RPE inhibited the diabetes-induced increases in the level of retinal inflammatory proteins, production of ROS, vascular leakage and retinal capillary degeneration." (PMID 36229454, 2022). "Our data support the premise that Akt2 cKO in the RPE has a protective effect against diabetes-induced retinal damage, including infiltration and activation of immune cells, by mediating the Akt1/GSK3β/NF-κB signaling axis." (PMID 36229454, 2022). "This inhibition suggests that decreasing Akt2 specifically in the RPE protects against diabetes-induced inflammatory changes in the neural retina." (PMID 36229454, 2022). "We also reported that MT not only has antioxidant effect in diabetes, but also preserves the function of Akt2 and its downstream glucose metabolic pathways under diabetic conditions." (PMID 34053181, 2021). "More genes are shared between pairs of phenotypes: NPP1, AKT2 between diabetes and obesity, HNF1A, INSR and PPP1R3A between ovarian cysts and diabetes, and PTEN between ovarian cysts and obesity." (PMID 31307376, 2019). "Previous studies reveal that Akt2 knockdown results in a syndrome similar to diabetes and Akt2 is indispensable for glucose homeostasis." (PMID 30941042, 2019). "It is noteworthy that deletion of Akt2 prompts onset and development of type 2 diabetes mellitus with time although our current finding does not indicate that there is any diabetic phenotype at the young and old ages examined in our study." (PMID 28681509, 2017). "So, to determine the mechanisms of antidiabetic effect of liraglutide, we investigated the expression of Akt2 in diabetes treated with liraglutide." (PMID 25183970, 2014). "Significant increase in p-Akt2/Akt2 ratio was observed in normal mice compared with diabetic mice, which proved that Akt2 was a major modulator of diabetes." (PMID 25183970, 2014). "AKT1 is ubiquitously expressed, while AKT2 is predominantly expressed in brown fat and the heart, correlating with the role of AKT2 in diabetes and glucose metabolism." (PMID 21869924, 2011). "This is the first time to report that the upregulation of insulin signaling proteins (IRS-1 and AKT-2) was obtained in a STZ-induced diabetic rat under ICT by EA." (PMID 21754922, 2011). "Since EMT in RPE cells is related to the pathogenesis of subretinal fibrosis, which is closely associated with the development of PDR and diabetic macular edema, we speculate that the diabetes-induced fibrosis process could be rescued in Akt2 cKO mice." (PMID 37443129, 2023).
diabetes (continued). "Notably, RPE-specific Akt2 cKO reversed the diabetes-induced impairment of the retina and RPE function." (PMID 36229454, 2022). "The severity of diabetes in the Akt2 cKO mice was similar to Akt2fl/fl controls." (PMID 36229454, 2022). "RPE-specific Akt2 cKO successfully inhibited these diabetes-induced retinal abnormalities, supporting a role for the RPE in the development of DR and suggesting that Akt signaling in the RPE may be involved in maintaining retinal homeostasis." (PMID 36229454, 2022). "Akt2 cKO rescued these diabetes-induced molecular alterations." (PMID 36229454, 2022). "Importantly, Akt2 is the isoform that has been most studied in diabetes because it acts downstream of insulin receptor (IR) signaling." (PMID 36229454, 2022). "As expected, Akt2 cKO inhibited the diabetes-induced increase of phospho-Akt2 in the RPE." (PMID 36229454, 2022). "However, these diabetes-induced defects were strikingly reduced in the retinas of Akt2 cKO diabetic mice." (PMID 36229454, 2022). "AKT2 silencing prevents renal protection in mice with streptozotocin-induced diabetes." (PMID 36094934, 2022). "Thus, it is possible that Akt2 knockout in the RPE has a protective effect against diabetes through upregulated Akt1, further inhibiting a GSK3β/NF-κB-regulated inflammatory response." (PMID 36229454, 2022). "Also, diabetes increased the expression of Foxo1 and Pepck genes and decreased Akt2 gene expression." (PMID 34848753, 2021). "The kinase AKT2 (PKB) is an important mediator of insulin signaling, for which loss-of-function knockout (KO) mutants lead to early onset diabetes mellitus, and dominant active mutations lead to early development of obesity and endothelial cell (EC) dysfunction." (PMID 31835296, 2019). "Induction of PAI-1 (total and active), IL-8, CCL2, and E-selectin in AKT2 KO cells is consistent with hyperinsulinemia and hyperglycemia in patients or with experimental animal models with diabetes and promotes recruitment of immune cells that stimulate inflammation." (PMID 31835296, 2019). "Mice lacking Akt2 developed type 2 diabetes mellitus, and Akt2 mutation has also been described in patients with type 2 diabetes mellitus." (PMID 31030467, 2019). "There had been several reports that argued the relationship between diabetes and Akt2." (PMID 25183970, 2014). "In addition, Akt2 knockout diabetic mice exhibit significantly lower levels of fibrotic changes indicating diabetes-induced retinal fibrosis could be mediated by the PI3K/Akt2/ERK signaling axis." (PMID 40689128, 2025). "Therefore, to investigate the potential role of Akt2 in the diabetes-induced retinal fibrosis process, we generated RPE-specific Akt2 conditional knockout (cKO) mice and induced diabetes in these mice and Akt2fl/fl control mice by intraperitoneal injection of streptozotocin." (PMID 37443129, 2023). "Immunoblotting confirmed this finding and further supported our hypothesis that knocking out Akt2 in RPE attenuates the diabetes-induced retinal fibrosis process by demonstrating that other fibrosis markers including collagen IV, CTGF, and fibronectin showed the similar pattern in the RPE." (PMID 37443129, 2023). "AKT2 influences glucose metabolism, and humans lacking functional AKT2 are predisposed to diabetes." (PMID 32977414, 2020). "Moreover, severe diabetes, age-dependent loss of adipose tissue, and mild growth deficiency were observed in mice lacking AKT2." (PMID 22680924, 2012). "Here, we describe the phenotype of early diabetes in a colony of NOD mice, with spontaneous invalidation of Akt2, that we called HYP." (PMID 38643275, 2024). "In summary, deletion of Akt2 in the RPE inhibits the diabetes-induced elevation of EMT and fibrosis markers, and prevents the diabetes-induced alteration of the tight junction proteins." (PMID 37443129, 2023).
diabetes (continued). "Here, we demonstrate that knocking out Akt2, specifically in the RPE, attenuated the diabetes-induced increase in fibrotic markers including CTGF, Collagen IV, Fibronectin, and alpha-SMA, suggesting the involvement of Akt2 in the fibrosis process of DR." (PMID 37443129, 2023). "Similar to the retina, the diabetes-induced increase in ICAM-1 and iNOS protein was inhibited in the RPE from Akt2 cKO diabetic mice compared to the controls." (PMID 36229454, 2022). "The diabetes-induced increases in the level of inflammatory proteins iNOS and ICAM-1, and in the ratio of pIκB/IκB in the neural retina were inhibited in Akt2 cKO diabetic mice compared to Akt2fl/fl diabetic controls." (PMID 36229454, 2022). "Akt2 cKO inhibited such diabetes-induced changes in the RPE, as supported by the comparison of Akt2 cKO diabetic mice with Akt2fl/fl diabetic controls." (PMID 36229454, 2022). "The C/C cells showed differential binding affinity compared to C/T cells in some previously identified TCF7L2 target genes that are involved in diabetes, such as ACSL5, ATM, AKT2, LEF1, and PDK4." (PMID 32651957, 2020). "In the current study, we have investigated the mRNA levels of insulin receptor substrate 1 (IRS-1), PI3K, Akt-2, and GLUT-4 and GLUT4 protein in skeletal muscle of normal control, diabetes control and treatment groups." (PMID 32987623, 2020). "For example, recent studies have used metabolomics to reveal that restoring phenylalanine levels and modulating glutathione metabolism can identify drug targets such as AKT2 and PDK2 in diabetes and cancer models, thereby guiding precision drug design and repurposing." (PMID 40725110, 2025). "Akt2 KO mouse displays a diabetes-like phenotype, whereas Akt3 KO has a negative impact on brain development." (PMID 40313745, 2025). "ROS has been shown to stimulate the PI3K signaling and activate Akt2 in RPE under diabetic conditions, suggesting that retinal fibrosis in diabetes might be attributed to the increased ROS in the eye activating Akt2/ERK signaling." (PMID 37443129, 2023). "Diabetes induction in the floxed control mice decreased levels of the RPE tight junction protein ZO-1 and adherens junction proteins occludin and E-cadherin; these decreases were rescued in Akt2 cKO diabetic mice." (PMID 37443129, 2023). "Thus, we postulate that diabetes-induced EMT and fibrosis in diabetic mice RPE cells is due to PI3K/Akt2/MAPK signaling." (PMID 37443129, 2023). "This suggests that inhibition of diabetes-induced retinal molecular modifications and pathological changes in the RPE of Akt2 cKO mice may be due to the upregulation of Akt1 and the downstream inhibition of the GSK3β/NF-κB regulated inflammatory response." (PMID 36229454, 2022). "In 10 month-old mice, the amount of albumin that leaked in the neural retina was higher in Akt2fl/fl diabetic mice compared to nondiabetic controls, while Akt2 cKO lowered such diabetes-induced leakage." (PMID 36229454, 2022). "To investigate further how the lack of Akt2 in the RPE protects the retina from diabetes-induced abnormalities, we focused on Akt1 and its downstream targets." (PMID 36229454, 2022). "We also found that the induction of diabetes increased the level of phospho-Akt2 (active Akt2), but not total-Akt2 in Akt2fl/fl diabetic mice compared to Akt2fl/fl nondiabetic controls." (PMID 36229454, 2022). "Similar to Akt2fl/fl RPE, diabetes increased the level of phospho-Akt2, but not total Akt2, in WT mice." (PMID 36229454, 2022). "Collectively, these results suggest that the RPE is not just passively affected by diabetes but also directly contributes to changes in the neural retina, and that Akt2 signaling in the RPE might play a central role." (PMID 36229454, 2022).
diabetes (continued). "We found that in the Akt2fl/fl samples, diabetes increased the level of phospho-Akt2 (but not total Akt2) and increased the ratio of phospho-NF-κB p65/total NF-κB p65, while decreasing phospho-Akt1 and the proportion of phospho-GSK3β/total GSK3β as compared to Akt2fl/fl nondiabetic controls." (PMID 36229454, 2022). "Interestingly, rod cell (stained with rhodopsin; green) morphology was similar between Akt2fl/fl and Akt2 cKO nondiabetic and diabetic mouse retinas (at a 2 month duration of diabetes)." (PMID 36229454, 2022). "To examine whether Akt2 in RPE could influence more broadly the expression of vasoactive mediators and cytokines generated in the retina and RPE, we evaluated inflammatory cytokines by ELISA after 2 months of diabetes." (PMID 36229454, 2022). "Further evidence on this issue represents the diabetes-like phenotype in mice lacking AKT2." (PMID 31752925, 2019). "Of the three human AKT isoforms (AKT1, AKT2, and AKT3), it has been suggested that AKT2 plays a specific role in insulin receptor signal transduction, implying that AKT2 may be a useful target for the treatment of diabetes mellitus." (PMID 23507778, 2013). "Furthermore, we show that in an Akt2 knockout mouse, specifically in the RPE, the diabetes-induced increases of RPE EMT markers in vivo and cell migration in vitro were significantly lowered, indicating that Akt2 signaling in RPE cells might contribute to the RPE EMT in DR." (PMID 37443129, 2023). "After an 8 months diabetes induction, we found increased expression of alpha-SMA in RPE flat mounts from diabetic Akt2fl/fl mice, but not in Akt2 cKO diabetic mice." (PMID 37443129, 2023). "This diabetes-induced increase of pro-inflammatory cytokines in the retina and RPE was essentially absent in the Akt2 cKO mice." (PMID 36229454, 2022). "While studies focusing on the distinct roles of the Akt1 and Akt2 isoforms in RPE during the development of DR have not been published, the idea that Akt may be involved in RPE cell EMT and retinal fibrosis in diabetes has recently surfaced." (PMID 37443129, 2023). "Further correlation analysis indicated the key molecules involved in PI3K-AKT signaling pathway, such as AKT1, AKT2, PIK3R1, and PIK3R2, showed significant positive correlations with AFAP1L2, and in which AKT1 also showed elevated expression in patients without diabetes history." (PMID 36434634, 2022). "Haplodeficiency of AKT1 in mice within an AKT2 null background can convert a pre-diabetic phenotype to overt type 2 diabetes, which is reversible by haplodeficiency of PTEN, whereas AKT3 does not appear to contribute significantly to diabetes." (PMID 22680924, 2012).